ALB (albumin)
Diseases named in the same sentence as ALB in open-access papers (continued):
Sharing a sentence is not in itself a finding about the gene and the disease.
Hypoalbuminemia (continued). "Serum albumin was not significantly different between the two groups (P = 0.32), and individuals with IBS were not more likely to have hypoalbuminemia (OR 2.36, 95% CI 0.29–19.05)." (PMID 32782953, 2020). "The mean ALB level was 2.6 g/dL in the DEX group and 2.7 g/dL in the non-DEX group; the number of patients with hypoalbuminemia (ALB of 3.5 mg/dL or less) was 90 (90%) in the DEX group and 89 (88%) in the non-DEX group." (PMID 32778146, 2020). "Hypoalbuminemia only occurs in severe AN patients and ABA mice did not exhibit an alteration of plasma albumin." (PMID 33202638, 2020). "In the present study, however, no hypoalbuminemia was observed in HIV-positive patients, but the mean albumin levels among the patients were lower compared to healthy individuals." (PMID 32148675, 2019). "Hypoalbuminemia was more common in CKD patients with DM than in those without DM as well, possibly due to increased urinary albumin excretion in patients with both CKD and DM that can lead to serum albumin leakage." (PMID 29290951, 2017). "The 3-month cumulative incidence of mortality was 21.4% in patients with both the absence of LC3 and hypoalbuminemia, compared to only 0.4% among those with both the presence of LC3 and serum albumin levels ≥ 3.5 g/dl." (PMID 29190884, 2017). "Multivariate analysis showed that in addition to other well-established prognostic factors, preoperative pre-albumin level was an independent predictor of CSS and OS, but not hypoalbuminemia." (PMID 27906675, 2017). "Finally, patients with MCD who are treated with corticosteroids often undergo a diuresis and natriuresis well before the serum albumin concentration starts to rise; this finding suggests that correction of the hypoalbuminemia might not be essential in steroid-induced natriuresis." (PMID 26793696, 2015). "While hypoalbuminemia has previously been reported in marmosets with MWS, we found that marmosets diagnosed with bone disease at necropsy also possessed lower serum albumin levels compared to animals without bone disease." (PMID 24324827, 2013). "Although we did not observe hypoalbuminemia (which could indicate sarcopenia), lower SKM might correlate with lower plasma albumin levels." (PMID 40563613, 2025). "The prevention and treatment of hypoalbuminemia are of clinical relevance in preventing infections, notably CDI in patients with cirrhosis, and serum levels of the effective albumin may be more significant." (PMID 35711246, 2022). "It has been proposed that strong hypoalbuminemia without differences in AST and ALT could be due to inflammation-driven escape of serum ALB into interstitial space downstream of increased vascular permeability." (PMID 33724185, 2021). "The incidence of hypoalbuminemia is high in our population due to selection bias and can not be extrapolated to the complete postsurgical HDU population, since only those cases in which the attending physician chose to measure albumin were included." (PMID 34099036, 2021). "Fourth, due to the lack of records of albumin, we did not perform albumin correction on the SAG, although some studies have shown that hypoalbuminemia could affect the SAG concentration." (PMID 33282007, 2020). "Albumin is a negative acute phase protein; therefore, release of proinflammatory cytokines (eg, IL‐6, TNF) leads to reduced albumin synthesis in the liver and to hypoalbuminemia in cancer patients." (PMID 35847697, 2020). "However, the mortality of those with a low albumin and normal CRP level did not increase, which indicated the increased mortality of hypoalbuminemia was partly attributed to inflammation." (PMID 32059708, 2020). "Multivariate analysis identified decreased preoperative pre-albumin level as an independent prognostic factor for CSS (HR 1.85, 95% CI 1.14-3.00, p=0.013) and OS (HR 1.73, 95% CI 1.12-2.70, p=0.015), but not preoperative hypoalbuminemia." (PMID 27906675, 2017).
Hypoalbuminemia (continued). "Strong correlation between hypoalbuminemia and mortality in PPU patients is not surprising when reduction of albumin synthesis is considered in cases of dehydration, hepatic dysfunction, cancer, critical clinical course, systemic inflammatory response syndrome and sepsis." (PMID 25722739, 2015).
Hypertension (1,694 papers, 1992 to 2026). The presence of chronic increased pressure in the systemic arterial system. "The logistic regression indicated that neutrophils (NE), the ratio of neutrophils to lymphocytes (NLR), platelet count (PLT), albumin (ALB) and triglycerides (TG) were independent risk factors for hypertension in children with obesity." (PMID 42291537, 2026). "Restricted cubic spline curves showed NE, NLR, PLT, ALB and TG increasing linearly with the risk of hypertension." (PMID 42291537, 2026). "Univariable regression analysis identified the number of Dectin-1+ cells, serum creatinine, blood urea nitrogen, serum albumin, urinary albumin-to-creatinine ratio, eGFR, and hypertension as factors associated with renal fibrosis in IgAN patients." (PMID 40959267, 2025). "The hypertension risk associated with an increase in albumin excretion was particularly high in women; the risk of hypertension was 2.47-fold higher compared to those with the group with the lowest albumin excretion." (PMID 40863329, 2025). "It was found that the red blood cell distribution width-to-albumin ratio (RAR) was significantly associated with the prevalence of hypertension, and this association exhibited a linear correlation feature." (PMID 40783688, 2025). "Other significant risk factors for a UACR increase included male gender, hypertension, higher HbA1c, higher serum albumin, and the use of SGLT2 inhibitors." (PMID 40566032, 2025). "The study, comprising 87 males and 63 females with newly and recently diagnosed hypertension, revealed a statistically significant association between elevated uric acid levels and decreased serum albumin levels (p=0.048)." (PMID 39897307, 2025). "The findings of this study highlight the potential of L. mutabilis albumin hydrolysate as a multifunctional ingredient for functional foods aimed at managing chronic conditions associated with oxidative stress, hypertension, and/or metabolic disorders." (PMID 40407487, 2025). "Risk factors for AKI development were male sex, history of hypertension, low albumin levels, and high [TIMP-2]⋅[IGFBP7] and NGAL levels." (PMID 39982587, 2025). "Albumin excretion within the normal range was independently associated with a higher risk of hypertension in the general population." (PMID 40863329, 2025). "In contrast, high baseline serum albumin levels were associated with factors related to metabolic syndrome such as alcohol consumption, hypertension, dyslipidemia, and fatty liver." (PMID 41248155, 2025). "In summary, anxiety state, high BMI, hypertension, high preoperative lipid levels or hyperlipidemia, and lower albumin levels on the third postoperative day were associated with an increased risk of DGE after PPPD." (PMID 40988445, 2025). "Our results revealed that male sex, history of hypertension, and low albumin levels were risk factors for CA-AKI." (PMID 39982587, 2025). "This study established a prediction model based on five independent risk factors: hypertension, serum albumin level, SOFA score, tidal volume, and respiratory rate." (PMID 40225039, 2025). "In the univariate analysis, the risk factors significantly associated with an elevated cardiovascular-related mortality risk included age, hypertension, underlying cerebrovascular disease, hemoglobin level, albumin, and a TG/HDL-C ratio greater than 3.29." (PMID 41283273, 2025). "The LASSO stability selection models were the only models to identify hand grip strength, dentures use, blue badge use, presence of hypertensive disease and serum albumin as high-risk variables in men." (PMID 41267842, 2025). "The results showed that BMI, high blood pressure, chronic bronchitis, peptic ulcer, operation way, anastomosis way, and postoperative albumin were independent risk factors for AL after esophageal cancer (p < 0.05)." (PMID 40956011, 2025).
Hypertension (continued). "After adjusting the model for age and sex (Model 2), high cumulative mean serum albumin levels remained significantly associated with a reduction in the incidence of hypertension." (PMID 38779492, 2024). "In contrast, the presence of hypertension, higher levels of albumin/creatinine ratio, and stage 5 CKD were independent risk factors of hypermagnesemia." (PMID 38791030, 2024). "After adjusting the model for age and sex (Model 2), the serum albumin high stable trajectory was significantly associated with a reduction in the incidence of hypertension (OR, 0.67, 95% CI, 0.52–0.90)." (PMID 38779492, 2024). "We also performed a risk stratification analysis of the lactate/albumin ratio for the primary endpoint across multiple subgroups, such as age, sex, hypertension, and cardiovascular disease." (PMID 39685564, 2024). "Hypertension, dyslipidemia, higher HbA1c, and high HbA1c levels were significantly positively associated with serum albumin levels and BMI categories." (PMID 38802949, 2024). "Logistic regression models were used to estimate the association between the 4 serum albumin trajectory groups and the risk of hypertension (Models 1–3)." (PMID 38779492, 2024). "High serum albumin levels reduced the risk of hypertension, using Q3 as a control, Q1 (OR, 1.30, 95% CI, 1.10–1.54), Q2 (OR, 1.08, 95% CI, 0.91–1.28), Q4 (OR, 1.03, 95% CI, 0.87–1.23) and Q5 (OR, 1.02, 95% CI, 0.86–1.21) (ptrend = 0.278)." (PMID 38779492, 2024). "Q1 of serum albumin at baseline was associated with an decreased incidence of hypertension (OR, 0.76, 95% CI, 0.61–0.95) (P < 0.001)." (PMID 38779492, 2024). "We sought to assess the risk of hypertension based on the trajectory of changes in serum albumin concentrations." (PMID 38779492, 2024). "With each 1-SD increase in cumulative mean serum albumin, the risk of hypertension decreased by 8% (OR, 0.92, 95% CI, 0.88–0.96)." (PMID 38779492, 2024). "Older age groups, men, those with hypertension, eGFR < 60 ml/min/1.73m2 and poor glycaemic control were most associated with higher values of albumin creatinine ratio." (PMID 38200427, 2024). "At the same time, previous longitudinal studies have described an association between serum albumin trajectories and risk of hypertension." (PMID 38779492, 2024). "A high stable trajectory of serum albumin concentrations (OR, 0.70, 95% CI, 0.51–0.96) was associated with a significantly lower risk of developing hypertension." (PMID 38779492, 2024). "Several observational studies have shown that serum total calcium is positively associated with hypertension, even when adjusted for serum albumin." (PMID 38505748, 2024). "Since inflammation is one of the known pathophysiological mechanisms of hypertension, one theory is that low serum albumin is associated with hypertension." (PMID 38779492, 2024). "A high stable trajectory of serum albumin concentrations was significantly associated with a reduced risk of hypertension in both males and overweight subjects." (PMID 38779492, 2024). "From 2009 to 2016, the cumulative mean and annual increases in serum albumin concentrations increased, and these increases were associated with the incidence of hypertension." (PMID 38779492, 2024). "Our study showed that the trajectory of serum albumin concentrations was only associated with the incidence of hypertension in males." (PMID 38779492, 2024). "Group-based trajectory models were obtained for 4 category groups, and logistic regression models were used to estimate odds ratios (ORs) and 95% confidence intervals (CIs) for each category group of serum albumin concentration and the risk of hypertension." (PMID 38779492, 2024). "In the crude model, the risk of hypertension decreased with an increase in cumulative mean serum albumin." (PMID 38779492, 2024).
Hypertension (continued). "We found that a moderate increase in serum albumin concentrations and a high stable trajectory were significantly associated with a reduced hypertension risk in subjects ≥45 years of age and of normal weight." (PMID 38779492, 2024). "Significant associations between cumulative mean serum albumin and the occurrence of hypertension were Q1 (OR, 1.07, 95% CI, 0.87–1.31), Q2 (OR, 0.96, 95% CI, 0.78–1.17), Q4 (OR, 0.86, 95% CI, 0.71–1.06) and Q5 (OR, 0.74, 95% CI, 0.60–0.92) (ptrend = 0.001)." (PMID 38779492, 2024). "Smoker, hypertension, dyslipidemia higher HbA1c and high HbA1c showed essentially the same association with serum albumin levels and BMI categories in the present study." (PMID 38802949, 2024). "After full adjustment using the model, cumulative average serum albumin values were associated with increased hypertension prevalence during 2009–2016 for Q5 (OR, 0.74, 95% CI, 0.60–0.92)." (PMID 38779492, 2024). "A longitudinal study of 3,872 participants in Japan found that for every standard deviation increase in the serum albumin concentration, the risk of hypertension decreased in both males and females." (PMID 38779492, 2024). "Our data also showed an association between the presence of hypertension and lower than normal levels of albumin and transferrin." (PMID 37323150, 2023). "There has been growing evidence in recent years that urine albumin excretion, even when it is within the normal range, is linked to an increased risk of hypertension." (PMID 37016928, 2023). "Compared with the deleted 1041 patients, the patients included in the study had slightly higher hypertension, chemotherapy, albumin, fasting blood glucose, BMI, and less surgery and risk of nutrition." (PMID 38156375, 2023). "Among the variables included in the final model, significant predictors of all-cause mortality included female gender, age, albumin level, active smoking, arterial hypertension, osteoporosis, and history of cancer." (PMID 37198577, 2023). "In men, the albumin level was significantly positively associated with high BMI and dyslipidemia, and inversely associated with age, current smoking status, and hypertension." (PMID 37700384, 2023). "Four risk factors were identified to be associated with increased risk of proximal DVT, including lower albumin level, hypertension, extended time to imaging and diagnosis of intertrochanteric fracture." (PMID 37507789, 2023). "In this study, we aim to explore the association of nutrition status defined by serum albumin (SA) levels and abdominal obesity with the prevalence and outcomes of clinical hypertension." (PMID 36937935, 2023). "Recently it was suggested that urine albumin‐to‐creatinine ratio (uACR), even within the normal range, can be associated with hypertension, but only a few studies have examined." (PMID 37016928, 2023). "Age at onset indirectly affected all-cause mortality through albumin (β = −0.089), heart failure (β = 0.114), and hypertension (β = 0.114)." (PMID 38831863, 2023). "The relationship between blood pressure and albuminuria is complicated and bidirectional, as hypertension can lead to worsened proteinuria resulting in renal damage and urinary albumin excretion rates associated with BP progression and hypertension incidence." (PMID 37041564, 2023). "Low serum albumin is associated with a higher risk of heart failure, hypertension, coronary artery disease, and stroke." (PMID 37284646, 2023). "Association between albumin (g/dL) and C-reactive protein (mg/L), stratified by sex, race/ethnicity, smoking and high blood pressure." (PMID 37653773, 2023). "Hypertension is associated with endothelial dysfunction, insulin resistance, inflammation, and oxidative stress, while ALB has anti-inflammatory and antioxidant effects." (PMID 36225955, 2022). "In univariate logistic regression analysis, age, hypertension, stage, Scr and albumin, ALI, anemia, surgery, and radiotherapy were all associated with cachexia in patients with lung cancer." (PMID 35898878, 2022).
Hypertension (continued). "According to previous studies, a number of risk factors, such as older age, hypertension, male sex, severe proteinuria, severely decreased serum albumin, and atherosclerosis, were found to lead to AKI in NS." (PMID 35912916, 2022). "Consistently, lysine administration to patients at risk for hypertension and kidney disease inhibited tubular albumin uptake, increased lysine conjugate formation, and reduced tricarboxylic acid (TCA) cycle metabolites, compared to kidney-healthy volunteers." (PMID 35835746, 2022). "Hypertension is a multifactorial disease that affects cardiovascular and renal systems, and persistently increased urinary albumin excretion (UAE) is a marker of cardiovascular risk progression and renal impairment." (PMID 35055008, 2022). "In a recent study among adult patients with hypertension, a U-shaped association between serum albumin levels and chronic kidney disease was also revealed by using cubic spline curves." (PMID 36110400, 2022). "We identified a common 24 ncRNA molecular signature related to hypertension-associated urinary albumin excretion, of which lncRNAs were the most representative." (PMID 35055008, 2022). "The PAPP-A level in the late first trimester, serum uric acid level, serum albumin level, serum total bilirubin level, and the eGFR were significantly associated with the severity of pregnancy-related hypertensive disorders." (PMID 36140589, 2022). "Univariate Logistic regression analyses showed that risk factors associated with CAD included NHR, smoking, hypertension, sex, age, creatinine, albumin, LDL-C, and central granulocyte (p < 0.05)." (PMID 33676400, 2021). "Charumathi and his associates documented that elevated serum total calcium levels were positively associated with hypertension after adjustments of serum albumin, 25(OH)D, serum phosphorus, and other confounders in a cross-sectional study of 12,405 US adults." (PMID 34912855, 2021). "Urine albumin/creatinine ratio (UACR) is an important marker of early renal damage (ERD) caused by hypertension." (PMID 34736407, 2021). "In this study, we found that there was a reverse relationship between serum albumin and the risk of incipient hypertension." (PMID 34050200, 2021). "They suggested that both serum calcium or albumin-corrected calcium was associated with an increased risk of hypertension." (PMID 34912855, 2021). "As a major protein in human serum, the low level of serum ALB is associated with increased risk of hypertension, cardiovascular disease, and carotid atherosclerosis." (PMID 33906674, 2021). "We found that participants with serum albumin ≤ 4.0 g/dL and polymorphisms of rs2894536 or rs10972486 had poor hypertension-free survival rate." (PMID 34050200, 2021). "In a study on a “relatively healthy Korean population”, higher levels of serum albumin did associate with obesity, high blood pressure and fasting glucose levels, as well as atherogenic dyslipemic profile and insulin resistance." (PMID 34078390, 2021). "As emphasized at the beginning of this review, CKD (as measured by albumin/creatinine) is a significant a risk factor for hypertension and cardiovascular disease." (PMID 32765290, 2020). "Increased urinary albumin excretion is associated with changes in ventricular remodeling in patients with hypertension." (PMID 32049171, 2020). "The delirium group had a higher average age and C-reactive protein level, and lower hematocrit, eGFR, and albumin readings, and more underlying hypertension." (PMID 33189145, 2020). "The combined analysis of GH and PE showed that albumin was correlated with the risk of pregnancy induced hypertension; the risk was 0.489." (PMID 32245416, 2020). "The risk factors significantly associated with the occurrence of SSI were hypertension, tuberculosis, low albumin (< 3.5 g/dl), blood glucose > 150 mg/dl, colon surgery, emergency surgery, colostomy/ileostomy and the higher NNIS risk index score (2 or 3)." (PMID 33183253, 2020).